GNAS (GNAS complex locus)
Diseases named in the same sentence as GNAS in open-access papers (continued):
Sharing a sentence is not in itself a finding about the gene and the disease.
cancer (continued). "In this study, 33 genes closely related to the Purinergic pathway (such as P2RY8, P2RX1, and GNAS) were selected, and their SNV, CNV, mRNA expression and methylation data were analyzed pan-cancer by bioinformatics methods." (PMID 38180750, 2024). "Seven reference genes (YWHAZ, GNAS, GAPDH, OAZ1, PTMA, B2M, and ACTB) were screened out among the 95 candidate reference genes from the data set of the platelets’ transcriptome of pan-cancer and 73 commonly known reference genes." (PMID 35770000, 2022). "The resulting CNV profiles of established cell lines showed concordance with previously reported data and highlight several gains and losses of cancer-related genes such as FGFR3 and GNAS." (PMID 35887203, 2022). "For instance, in the current sample, the genes GNAS, GNAQ, and GNA11 were widely altered across cancer types, and these alterations often were accompanied by specific genomic abnormalities in AURKA, CBL, and LYN." (PMID 34150649, 2021). "We further analyzed the expression of imprinted genes GNAS, GRB10, and SNRPN in 204 benign and 654 malignant samples across ten cancer types." (PMID 32448196, 2020). "For our study, all the GNAS, GRB10, and SNRPN genes shared a similar expression pattern in 753 cases of ten cancers." (PMID 32448196, 2020). "Using these results, imprinted genes GNAS, GRB10, and SNRPN were identified as the more efficient cancer biomarkers over IGF2 and IGF2R, specifically using our QCIGISH method." (PMID 32448196, 2020). "Some proteins of the guanine nucleotide‐binding protein subunits GNAQ (Gqα), GNAS (Gs‐α), GNB1(Gβ1), and GNA13 (Gα) were overrepresented in the Circadian entrainment pathway as well as in cancer pathway." (PMID 31282103, 2019). "This revealed that many cancers, beyond those showing GNAS hotspot mutations, display a tendency for widespread up-regulation of Gs activity over the other G-proteins, which is particularly evident for Gi/o which never prevails in any investigated cancer type (top)." (PMID 31337866, 2019). "In line with previous observations, genes involved in cancer development were represented on Bs of four studied species: red fox (KIT), Chinese raccoon dog (ENPP1, GNAS, HMGCR, KDR, RET), brocket deer (BCL6, RASA1, RET), and Korean field mouse (JAK3)." (PMID 30103445, 2018). "Various cancer-related genes were also differentially expressed significantly, including BRAF, BRCA2, VEGFA, VEGFB, RET, PIK3CA, CTNNB1 and GNAS." (PMID 27350898, 2016). "It is noteworthy that many genes within these pathways (e.g., AKT2, AKT3, CREBBP, MAPK1, GNAS, RPTOR) are already known to play relevant roles in cancer cell growth and proliferation, which could provide a plausible biological basis for such a link." (PMID 41226303, 2025). "However, of those genes included in the pPRS score, prior evidence links NSAIDs anti-cancer activity with β-catenin (CTNNB1), GNAS, and PTGER4, the extracellular receptor for PGE2 that is the major downstream prostanoid produced by PTGS-2." (PMID 40763299, 2025). "Notably, Patient 63 had a KRAS G12V, SMAD4, GNAS, and KMT2C mutant-positive PDAC with liver metastases while Patient 64′s cancer was BRAF V600E-positive, and they had also undergone treatment with experimental BRAF and MEK inhibitors." (PMID 39941724, 2025). "While previous studies have revealed that oncogenic GNAS mutants promote hyperplastic growth and tumorigenesis, our study demonstrates that they also promote immune evasion by repressing CXCL9/10/11 across human cancers." (PMID 37714844, 2023). "Although elevated anti-GNAS autoantibody was observed in other cancer patients, there was no detection and evaluation of the corresponding antigen." (PMID 38107305, 2023).
cancer (continued). "This possible mechanism explained that autoantibody to GNAS elevated in early-stage HCC patients without further increase as the cancer progressed." (PMID 35052777, 2022). "Moreover, focal CNA amplifications encompassed genomic peaks that harbored canonical cancer genes including those found at HPV-integrated hotspots (MYC, MYCN, MYCL, SOX2, NR4A2, and ANKRD12), and others (CCNE1, SMAD2, BCL2L1, and GNAS)." (PMID 36216793, 2022). "Several of these genes are related to cancer, including CD44, DST, GLS, GNAS, KIF1B and AHRR." (PMID 34086943, 2021). "Among these genes, TP73, GNAS, and NOTCH1 are notable ones with known relations to cancer." (PMID 33711952, 2021). "In summary, a series of DNA methylation surveys revealed that a relatively large fraction of imprinted genes are epigenetically affected in human cancers, and also that this epigenetic instability is particularly pronounced in a subset of imprinted genes, such as PEG3, IGF2, DLK1, MEST and GNAS." (PMID 26338779, 2015). "In addition, this case showed carcinoma-specific amplification of 7p (EGFR and BRAF) and 20q (ASXL1, AURKA, and GNAS), which were observed as clonal amplification for the three MSS cases without ERBB2 amplification." (PMID 26336987, 2015). "In addition, the diagnostic models developed from the BAE, MAE, and TE measurements of the imprinted gene panel GNAS, GRB10, and SNRPN could provide important predictive information which are useful in early-stage cancer detection and personalized cancer management." (PMID 32448196, 2020). "For example, the imprinted gene GNAS and the non-imprinted gene AURKA, both important in cancer pathogenesis, had nearly identical copy number in our data (ρ = 0.964, p0 < 2 × 10–308)." (PMID 36461044, 2022). "Although there was no shared gene among the three groups in the Cancer-related pathways, three genes were shared between the two malignant groups namely AR, HSP90AB1 and GNAS." (PMID 36686473, 2022). "Nevertheless, in this study expanding the molecular analysis with genes from the Ampliseq cancer hotspot panel v2 beyond KRAS and GNAS did not significantly improve the detection of mucinous PCN (data not shown)." (PMID 31258847, 2019).
adenocarcinoma (17 papers, 2012 to 2026). A common cancer characterized by the presence of malignant glandular cells. "GNAS mutations are rare in adenocarcinomas arising in the gastrointestinal tract and are considered histologically specific genetic mutations." (PMID 40463821, 2025). "Despite the rarity of GNAS mutations in adenocarcinomas, both gastric-type duodenal adenomas and adenocarcinomas frequently harbor GNAS mutations." (PMID 40463821, 2025). "In contrast, GNAS mutations have been detected in all gastric-type adenocarcinomas." (PMID 40463821, 2025). "GNAS wild-type and gastric-type IPMNs are significantly associated with adenocarcinoma development." (PMID 39594780, 2024). "In agreement with the previous study, our results suggest that KRAS and GNAS mutational pattern may represent different pathways in the IPMN-adenocarcinoma sequence." (PMID 27512631, 2016). "The KMT2D, GNAS, EP300, GRM3, and PIK3CG mutations were all significantly higher in patients with squamous than those with adenocarcinoma (P = 0.0066, P = 0.019, P = 0.0075, P = 0.017, and P = 0.0075, respectively)." (PMID 37301854, 2023). "GNAS mutation was significantly associated with high-grade dysplasia, whereas wild-type GNAS in IPMNs was significantly related to the development of adenocarcinoma." (PMID 27512631, 2016). "Another notable differential interaction selected by BNKL is GNAS→ADCY6 (activation in adenocarcinoma and suppression in SQCC) while, according to KEGG, in normal cells we have a stimulating effect of GNAS, the gene encoding the G-protein, on ADCY6." (PMID 24565081, 2013). "In addition, the frequencies of KRAS and GNAS mutations in IPMNs are highly variable according to the microscopic duct subtypes, reflecting their independent roles in the IPMN-adenocarcinoma sequence." (PMID 27512631, 2016). "Correspondingly, GSP encoded by GNAS was present in IPMN but not in associated adenocarcinoma." (PMID 37304241, 2023). "Interestingly enough, GNAS mutation rates in IPMN with pancreatic adenocarcinoma were recently found to be significantly decreased when compared with cases of IPMN without associated adenocarcinoma." (PMID 39594780, 2024). "GNAS mutation was present in 80 (51 %) of 157 IPMN patients with invasive adenocarcinoma, whereas 265 (59 %) of 446 IPMNs without adenocarcinoma." (PMID 27512631, 2016). "The subgroup analyses disclosed that the ethnicity and detection methods of these mutations did not influence the relationship between GNAS mutation and IPMN-associated adenocarcinoma." (PMID 27512631, 2016).
genetic disease (12 papers, 2008 to 2026). "McCune–Albright syndrome (MAS) is a rare genetic disorder caused by somatic activating variants of the GNAS gene." (PMID 40357201, 2025).
endocrine disorders (11 papers, 2016 to 2026). "The detection of the GNAS p.R201 variants in blood circulating cell free DNA has been shown to be effective for diagnosis of FD/MAS for those with endocrinopathy or high skeletal burden score." (PMID 38326833, 2024). "Pseudohypoparathyroidism (PHP) is a rare endocrine disease characterized by resistance to the action of the parathyroid hormone (PTH), which is divided into PHP1 caused by (epi)genetic defects of GNAS gene which encodes stimulatory guanine nucleotide-binding protein (Gsα)." (PMID 36465610, 2022).
metabolic disease (6 papers, 2011 to 2025). A congenital disorder (due to inherited enzyme abnormality) or acquired (due to failure of a metabolically important organ) disorder resulting from an abnormal metabolic process. "Taken together, these data suggest that GNAS mutations or variants that reduce Gαs activity could contribute to metabolic disorders, including suboptimal insulin secretion." (PMID 40526441, 2025). "Our data imply that increased methylation at GNAS DMR may be among the mechanisms linking maternal GDM with high risk of metabolic diseases in later life of fetuses." (PMID 25269528, 2014). "We concluded maternal GDM-induced hypermethylation at GNAS DMR and this condition may be among the mechanisms associating maternal GDM with increased risk of metabolic diseases in later life of offspring." (PMID 25269528, 2014). "The aim of this study was to clarify the alteration in methylation levels at differentially methylated regions (DMRs) of GNAS and IGF2 in fetuses of GDM women and to explore the possible mechanisms linking maternal GDM with high risk of metabolic diseases in later life of GDM offspring." (PMID 25269528, 2014). "Among the validated genes, GNAS encoding the heterotrimeric Gs protein alpha-subunit (Gsα) that increases intracellular cAMP and activates PKA, promoting Ca2+ influx and insulin secretion by pancreatic β-cells, has been shown to be involved in both cardiac and metabolic disorders in humans." (PMID 37628941, 2023).
infection (5 papers, 2021 to 2025). The state of being infected such as from the introduction of a foreign agent such as serum, vaccine, antigenic substance or organism. "We discovered that 48 h post-infection, the expression levels of GNAS, PRKACA, RAP1A, and VAMP8 were all dramatically downregulated, which inhibited Rap1 activation and transactivation." (PMID 37211158, 2023).
bone disorder (3 papers, 2013 to 2020). "Fibrous dysplasia (FD) is a rare bone disorder that is caused by a missense mutation of the GNAS gene, leading to improper function of the alpha subunit of the heterotrimeric G protein (Gsα) that ultimately results in a local disorder of bone formation." (PMID 29022055, 2018).
endocrine neoplasms (3 papers, 2014 to 2018). "The endocrine tumours with activating GNAS mutations have been supposed to be associated with hormonal secretion." (PMID 27512631, 2016). "GNAS mutations had been identified in several tumors of the endocrine system." (PMID 29876008, 2018). "Interestingly, most of the GNAS mutations at codon 201 in IPMNs result in either an R201H or an R201C substitution, which are the same mutation as in endocrine neoplasms." (PMID 27512631, 2016).
brain diseases (1 paper, 2023). "Interestingly, clustered small genomic deletions at chr20:58888852–58890100 are located in exon 1 of the GNAS isoform, which suggests that a specific isoform of GNAS contributes greatly to brain diseases." (PMID 36869069, 2023).
hematological disorders (1 paper, 2022). "Also, for GNAS reported evidence underlines its involvement in both genetic and hematological diseases." (PMID 36035165, 2022).
hematological neoplasms (1 paper, 2016). "Somatic activating mutations in GNAS are common in solid tumors but were recently identified for the first time in hematological neoplasms, in 1% of MDS." (PMID 27486981, 2016).
GNAS also shares sentences with these, for which no sentence is quoted: somatotroph adenomas (8 papers); Cafe-au-lait spot (5); hyperthyroidism (5); benign tumors (4); hypercortisolism (4); hypoparathyroidism (4); acute myeloid leukemia (3); adrenal hyperplasia (3); developmental delay (3); liver cancer (3); mucinous adenocarcinoma (3); neuroblastoma (3); Ovarian cyst (3); ACTHomas (2); adenomas of the colorectum (2); adenosquamous carcinoma (2); autism (2); autoimmune hyperthyroidism (2); Bardet-Biedl syndrome (2); biliary tract cancer (2); colorectal tumors (2); endometrial cancer (2); fibrosarcoma (2); gastrointestinal disease (2); Intellectual disability (2); kidney cancer (2); Lyme disease (2); lymph node metastases (2); neuroendocrine tumors (2); pancreatic endocrine tumours (2).
A further 131 diseases each share a sentence with GNAS in 2 papers or fewer.